GDNF (glial cell derived neurotrophic factor)
Diseases named in the same sentence as GDNF in open-access papers (continued):
Sharing a sentence is not in itself a finding about the gene and the disease.
tumor (continued). "In pancreatic cancer, GDNF and its receptors are widely expressed, promoting tumor proliferation, invasion, and perineural infiltration through integrin β1 and matrix metalloprotease-9 (MMP-9) upregulation." (PMID 40642294, 2025). "Neurotrophic factors, including NGF and GDNF, are critical mediators of tumor innervation, playing a pivotal role in recruiting nerves and promoting neurogenesis within the TME." (PMID 41009819, 2025). "In ACC, a key signaling axis involves tumor-derived CCL2 recruiting CCR2+ TAMs, which in turn secrete GDNF to drive tumor cell proliferation via the RET pathway." (PMID 41164198, 2025). "From a therapeutic perspective, targeting key molecular drivers of spontaneous neurogenesis—including NGF, GDNF, VEGF, and the TGF-β/Smad3 pathway underlying MNT—represents a promising approach to mitigating the adverse effects of tumor innervation." (PMID 41009819, 2025). "Neurotrophic factors (e.g., NGF, BDNF, GDNF) and axon guidance molecules (e.g., semaphorins, netrins, ephrins) mediate this integration, promoting neural remodeling and facilitating tumor innervation." (PMID 41009819, 2025). "Tumor‐associated macrophages (TAMs) are enriched at PNI sites, where they secrete glial cell line‐derived neurotrophic factor (GDNF) to promote cancer‐nerve crosstalk, making TAM reprogramming a clinically promising anti‐PNI strategy." (PMID 40985319, 2025). "GDNF, initially isolated from rat glial cell lines, is closely associated with the PNI in tumor tissues, with motor nerves and skeletal muscles serving as significant sources, and exercise shown to increase its protein levels in tissues." (PMID 39492832, 2024). "Mechanistically, endoneurial macrophages support tumor cell growth by secreting high levels of GDNF." (PMID 39402303, 2024). "Tumor migration is sustained by perivascular macrophages expressing glial-derived neurotrophic factor (GDNF), and disruption of the NCAM-GDNF axis limits metastatic growth in leptomeninges." (PMID 39402303, 2024). "Pain-like behaviors are observed prior to tumor formation and are regulated by enhanced glial cell line–derived neurotrophic factor (GDNF) expressed by SCs." (PMID 38258905, 2024). "GDNF can promote the proliferation and metastasis of malignant tumor cells through the RET-SRC-HER2 and RET-AKT signaling pathways." (PMID 38699694, 2024). "Through the PI3K/AKT/EGR-1 pathway, CD74 enhances tumor invasion and promotes neuroplasticity by increasing GDNF secretion, thereby facilitating tumor invasion." (PMID 38099290, 2023). "Although not previously reported in MASLD, CHRDL2 is upregulated in a range of tumor tissues including HCC49, while STC1, CTGF50, GDNF and FGF7 are all linked to hepatic fibrogenesis." (PMID 37903863, 2023). "The anti-inflammatory function of testosterone is attenuated by the cytokines and oncogenes secreted by cancer cells and pro-inflammatory macrophages to favor damaged microglia cells’ survival and proliferation via GDNF upregulation necessary for tumor growth." (PMID 37833789, 2023). "Macrophage-derived IL-1β induces non-neuronal cells to synthesize nerve growth factor (NGF), and activated macrophages can also release glial cell-derived neurotrophic factor (GDNF)-activated RET receptors to trigger tumor cell migration." (PMID 36900158, 2023). "The expression and rapid release of NRG1 in neurons and their axons can be stimulated by NGF, BDNF, NT-3, and GDNF, which are extremely abundant in tumor microenvironment." (PMID 36900158, 2023). "Glioma cells release GDNF (Glial cell line-Derived Neurotraphic Factor), a chemotactic agent that recruits microglia to the tumor region and also induces a shift to a pro-tumor phenotype." (PMID 37700840, 2023). "The immunostaining of tumor tissue indicated a high level of GDNF and NRF2-positive cells in testosterone-treated tumor tissue compared with their respective control groups, which showed low GDNF and NRF2-positive cells." (PMID 37833789, 2023).
tumor (continued). "In conclusion, these results suggest that GFRA1, which is highly expressed in GC cells, relies on TAM-derived GDNF to promote tumor cells to resist apoptosis and to form liver metastases." (PMID 36808605, 2023). "We investigated a potential cooperation between NLGN1 and the neurotrophic factor glial cell line derived neurotrophic factor (GDNF) because this factor is known to play a function in tumor–nerve interactions." (PMID 36499024, 2022). "Even though GFRα1 expression varies widely in different cancer cells, both GFRα1 and its ligand GDNF can be released from the tumor microenvironment and cooperate to facilitate cancer invasion." (PMID 35582425, 2022). "Nine days after the inoculation of tumor cells, we found that the expression of GDNF in the BCP group was significantly decreased compared with that in the Sham group." (PMID 36138924, 2022). "Astrocytes in the peritumoral areas express the Glial Cell Line-Derived Neurotrophic Factor (GDNF) to facilitate the invasive tumor growth." (PMID 35205842, 2022). "The inflammatory process can also modify the tumor environment and the overexpression of cytokines involved in the expression of glial cell-derived neurotrophic factor (GDNF) and FGF-1 results in the proliferation of epithelial and glandular stromal cells." (PMID 35681707, 2022). "Further investigation demonstrated that miR-196a-5p represented its function through modulation of glial cell line-derived neurotrophic factor (GDNF) as a neurotrophic factor affecting tumor invasion and metastasis." (PMID 35676702, 2022). "Because of the established role of the neurotrophic factor glial cell line-derived neurotrophic factor (GDNF) in tumor–nerve interactions, we assessed a potential NLGN1–GDNF cooperation." (PMID 35053395, 2022). "Tumor invasion of nerves is upregulated upon GDNF induction and is greatly diminished when GDNF/GFRa1/RET pathway is suppressed." (PMID 35223829, 2022). "While caspase activities are decreased, increases in GDNF levels tend to promote abnormal T-cell and tumor-initiating cell survival." (PMID 35392088, 2022). "For example, during tumor initiation, GDNF (a TGF-β family member) was found to be impeding anti-tumor immune cells activities but instead transforming the cells into tumor-associated immune cells." (PMID 35392088, 2022). "SDF-1 and GDNF are other proposed factors that have been shown to promote TAM accumulation inside the tumor." (PMID 33766119, 2021). "Nerve derived macrophages, recruited and activated by cancer cells in neuro-tumor microenvironment have been demonstrated to assist tumor cells in invading towards nerve through secreting GDNF in vitro." (PMID 34187567, 2021). "A small modification in the niche significantly affects cell–cell contact and tumor initiation via the secretion of neuroprotective proteins like GDNF or hormones (dopamine) and cancer stem cell markers." (PMID 34513834, 2021). "Microglia are recruited to the TME by pro-migratory signals such as granulocyte-macrophage colony-stimulating factor (GM-CSF), stromal derived factor-1 (SDF-1), and glial cell line-derived neurotrophic factor (GDNF) secreted by tumor cells." (PMID 34571905, 2021). "Tumor-activated endoneurial macrophages secrete higher levels of glial-derived neurotrophic factor (GDNF)." (PMID 33322770, 2020). "The majority of the tumors show stromal staining; positive GDNF staining of tumor cells was noted in only 7 of 82 patients in the SU cohort and 45 of 189 patients in the WU cohort." (PMID 32084217, 2020). "Of the 604 patients in the TCGA cohort, we focused on 377 patients who have a complete set of information including age, gender, tumor site, nodal and tumor staging classification, GDNF, NCAM, GFRA and RET mRNA expression data for multivariate analysis." (PMID 32084217, 2020). "Previously, it was reported that the GDNF/GFRα/RET system is involved in tumor cell proliferation, invasion and migration." (PMID 32438692, 2020).
tumor (continued). "Paracrine signaling has been implicated in perineural invasion, with factors secreted by nerves, including glial cell line derived neurotrophic factor (GDNF), increasing the invasion of tumor cells along the nerves." (PMID 31921388, 2019). "Intriguingly, in MCF7 xenografts, GDNF was related to the tumor infiltrating fibroblasts (TIF) and the invasive margin of the lesion." (PMID 35582269, 2019). "GDNF was demonstrated to promote the proliferation and invasion of tumor cells through phosphorylating its receptor RET." (PMID 31024838, 2019). "Tumor methylation data were used to build a methylation signature of PTEN loss in our cohort, which was confirmed in TCGA, and included CpGs in ATP11A, GDNF, JAK1, JAM3, and VAPA." (PMID 29137428, 2017). "Together, these findings support an important role for tumor microenvironment damage responses in modulating treatment resistance and identify the GDNF signaling pathway as a potential target for improving responses to conventional genotoxic therapeutics." (PMID 25575823, 2015). "GDNF has a chemotactic effect on tumor cells and increases the production of metalloproteinases (2 and 9)." (PMID 25408713, 2014). "Other chemoattractants that have been shown to stimulate microglia/macrophage migration into the tumor include colony stimulating factor-1 (CSF-1), macrophage colony-stimulating factor (M-CSF), and glial-derived neurotrophic factor (GDNF)." (PMID 23983766, 2013). "For example, GDNF appears to promise substantial specificity and sensitivity due to frequently highly elevated DNA methylation of this locus in tumor tissues." (PMID 18616821, 2008). "Of these, eight showed highly significant hypermethylation in tumor tissue (p < 0.0001): GDNF, MTHFR, OPCML, TNFRSF25, TCF21, PAX8, PTPRN2 and PITX2." (PMID 18616821, 2008). "Future studies should explore whether GDNF functions as a context-dependent modulator of hormone signaling or tumor progression in EC." (PMID 41262902, 2025). "Further, pathway analyses using scRNA-Seq data from DhhCre Nf1fl/fl mice prior to any tumor formation, at 2 months of age, indicate that of all signaling pathways that are predicted to be increased in SCs for communication with neurons, GDNF signaling is the only one specifically elevated." (PMID 38258905, 2024). "SERPINE1 knockdown suppressed tumor progression promoted by GDNF." (PMID 39337713, 2024). "In addition, we found that the GFRA1 protein was mainly expressed on the surfaces of the tumor cells, and that GDNF was mainly expressed in stromal cells." (PMID 36808605, 2023). "The clinical relevance of these findings was verified through the detection of increases in both RET expression and GDNF-regulated transcriptional pathways in recurrent tumor samples (73.1%) compared to 55.8% of primary tumors, which was reproduced in analysis of the TCGA and NIH ROCK databases." (PMID 36918928, 2023). "In this study, we hypothesized that testosterone regulates neuroinflammation and GDNF upregulation to favor tumor formation and development." (PMID 37833789, 2023). "The crucial role of GDNF in regulating SSC numbers was shown when mice with impaired GDNF signaling showed a gradual loss of SSCs, while its pan-ectopic overexpression promoted germ cell hyperplasia and ultimately tumor formations." (PMID 37759457, 2023). "While this observation may suggest a relationship between GDNF expression and tumor environmental factors, detailed mechanistic studies of secreted factors are a technical challenge, and remain a limitation in this area of research." (PMID 36918928, 2023). "Neurotrophic factors such as NGF and GDNF can be released either by tumor cells or neurons." (PMID 35223829, 2022). "For instance, in an in vitro experiment in which human umbilical vein endothelial cells (HUVECs) have been used to mimic the tumor microenvironment GDNF was able to stimulate the hepatic growth factor (HGF) production and consequently the phosphorylation of its main receptor MET." (PMID 33806299, 2021).
tumor (continued). "However, GDNF and its related family members have been shown to enhance tumor aggressiveness by increasing tumor cell migration and promoting perineural invasion." (PMID 32084217, 2020). "In addition, GDNF is induced in vitro by TNF-± and IL-1β, inflammatory cytokines secreted by tumor-associated macrophages (TAM) in BC." (PMID 35582269, 2019). "Moreover, tumor-derived-conditioned medium induced the expression of glial-cell-derived neurotrophic factor by TAMs on mRNA and protein level, which was involved in promoting proliferation, migration, and invasion of SACC cells." (PMID 31921102, 2019). "TAMs were documented to express a high level of GDNF, which could promote the proliferation and invasion of the tumor cells." (PMID 31024838, 2019). "Therefore one possibility is that GDNF becomes expressed after tumor cells are “primed” with GDNF by another cell in the microenvironment." (PMID 29608602, 2018). "Recent data have suggested that RET variants or amplification may also occur in ∼1% of breast tumors or metastases, while tumor-specific expression of GDNF and ARTN is relatively frequent and can promote autocrine activation of RET downstream signaling." (PMID 30666215, 2018). "In tumor xenografts, they showed that the inflammatory cytokines tumor necrosis factor-α and interleukin-1β act synergistically to up-regulate GDNF expression and this effect is mediated by a GDNF/GFRA1/RET axis." (PMID 29617307, 2018). "This may suggest that GDNF expression is initiated in tumors by another stimulus-dependent pathway or introduced by another cell type in the tumor microenvironment." (PMID 29608602, 2018). "Indeed, both the cell viability and the size of tumor spheres were significantly increased by GDNF treatment and this GDNF-mediated increase was fully blocked by NVP-AST487 treatment." (PMID 27602955, 2016). "Together, these data show that cancer therapeutics, such as IR or chemotherapy, to which tumor microenvironment cells are often exposed, induce GDNF secretion in these tumor microenvironment cells which then stimulates the stromal cells in an autocrine/paracrine loop via the SRC/ERK pathway." (PMID 25575823, 2015). "As the tumor microenvironment is comprised of tumor cells and benign constituents including fibroblasts, we determined whether GDNF exhibits paracrine and/or autocrine effects toward this abundant benign cell type." (PMID 25575823, 2015). "A local source of GDNF in the tumor stroma could therefore act as an additive factor in TME remodeling and survival after therapy." (PMID 25575823, 2015). "Exposure to GDNF also induced tumor cell resistance to mitoxantrone and docetaxel chemotherapy." (PMID 25575823, 2015). "Nevertheless, it is unclear whether GDNF facilitates tumor progression via SERPINE1 in GBMs." (PMID 39337713, 2024). "Similarly, other NFs such as GDNF promote their growth when released by tumor cells." (PMID 39682125, 2024). "The RET/GDNF tyrosine-kinase survival pathway could generate tumour promoting proliferative events." (PMID 34588620, 2021). "Finally, GDNF has been shown to be elevated in PCa reactive tumor stroma and, as such, may contribute to tumor growth and invasion." (PMID 29137428, 2017). "Studies have shown that SCs can specifically activate receptor tyrosine kinase family members on the surface of tumor cells (including the RET, TrkA, TrkB) by secreting GDNF, NGF, and BDNF." (PMID 41583906, 2026). "Genes with reported anti-tumor functions, including SCGB1D2 (Secretoglobin Family 1D Member 2, lipophilin B), FKBP5, CD52, DLK1, GALNT9, GNG2, GDNF, and TMEM35A, were significantly upregulated after CUDC-907 + MPA treatment and validated by RT-PCR." (PMID 41262902, 2025). "This phenomenon emerges intrinsically within the TME, driven by tumor-derived neurotrophic factors such as NGF, GDNF, and vascular endothelial growth factor (VEGF), which stimulate axonal sprouting and nerve fiber formation directly within tumors." (PMID 41009819, 2025).
tumor (continued). "Mechanistic studies implicate neurotrophin and axon−guidance signaling (e.g., GDNF–RET, NGF–TrkA) and Schwann−cell reprogramming as drivers of neural tracking and extracellular−matrix remodeling at the nerve–tumor interface." (PMID 41445745, 2025). "We also focused on other biomarkers playing an important role in tumor formation and growth, such as angiogenic factor VEGF (vascular endothelial growth factor), GDNF (glial cell derived neurotrophic factor) and chemokine fractalkine/CX3CL1." (PMID 39796185, 2025). "Schwann cells also release neurotrophic factors, such as GDNF, through paracrine signaling, which binds to the rearranged during transfection (RET) receptor on PDAC cells, promoting tumor cell migration toward neurons." (PMID 39492832, 2024). "Research shows that cancer cells express neurotrophic markers such as NGF, GDNF, and brain‐derived neurotrophic factor (BDNF), releasing axon‐guiding molecules that promote axonogenesis and attract nerves to the tumor site." (PMID 39492832, 2024). "Mounting evidence suggests that malignant cells influence the tumor microenvironment (TME) by releasing a plethora of neurotrophic factors, e.g. NGF, BDNF, GDNF, Neuturin and Ephrin B1 to promote axonogenesis, neurogenesis and neural reprogramming." (PMID 39592661, 2024). "GDNF-mediated activation of RET is recognized in several cancers and promotes tumor growth, invasion, and metastasis." (PMID 37691636, 2023). "In general, we conclude that during GC liver metastasis tumor cells express GFRA1 and are highly dependent on GDNF secreted by TAMs in the microenvironment at the invasive margin." (PMID 36808605, 2023). "In the present study, the lentivirus was intrathecally injected on POD 7 after tumor cell inoculation, and the spinal cord was harvested on POD 15 to observe the expression of GDNF." (PMID 36138924, 2022). "Other neurotrophic factors such as brain-derived neurotrophic factor (BDNF) and glial cell-derived neurotrophic factor (GDNF), have been shown to induce tumor migration via upregulation of VEGF and activation of p38 and PI3K/Akt signaling pathway." (PMID 35223829, 2022). "TAMs are recruited to the tumor site through tumor secretion of cytokines and chemokines, including ATP, CSF-1, CCL2, GDNF, GM-CSF HGF/SF, MCF-3, SDF-1, TNF and VEGF6,15." (PMID 32555306, 2020). "The most important carcinogenic mechanism and cellular dysfunctions at this stage of CRC are as follows: MIR133B is modified by DNA methylation to downregulate GDNF and SMC2, inhibiting tumor proliferation and migration." (PMID 32211020, 2020). "Owing to the epigenetic effect, the target gene SMC2 promotes tumor apoptosis and inhibits the cell cycle; the target gene POU2F1 inhibits cell proliferation; and the target gene GDNF inhibits cell migration and proliferation." (PMID 32211020, 2020). "Furthermore, the high expression of GDNF may affect tumor migration." (PMID 32211020, 2020). "NVP-AST487 acted as the best inhibitor abrogating the GDNF-RET pathway and the growth of 3D tumor spheroids." (PMID 35582269, 2019). "The β-values of GDNF and FGFR1 were representatively shown, and significantly lower in FAP IME neoplasms than sporadic IME CRC (P = 3 × 10−5 and P = 0.02, respectively)." (PMID 30220972, 2018). "The expression of GDNF (by glia or fibroblasts), and its cognate receptor RET, in organoids and the parental tumor implies crosstalk between glia and tumor cells." (PMID 30353124, 2018). "The most effective inhibitor identified, NVP-AST487, suppressed GDNF-stimulated RET downstream signaling and 3D tumor spheroid growth." (PMID 27602955, 2016).